SBDS (SBDS ribosome maturation factor)
Description:
Required for the assembly of mature ribosomes and ribosome biogenesis. Together with EFL1, triggers the GTP-dependent release of EIF6 from 60S pre-ribosomes in the cytoplasm, thereby activating ribosomes for translation competence by allowing 80S ribosome assembly and facilitating EIF6 recycling to the nucleus, where it is required for 60S rRNA processing and nuclear export. Required for normal levels of protein synthesis. May play a role in cellular stress resistance. May play a role in cellular response to DNA damage. May play a role in cell proliferation.
Synonyms: CGI-97; FLJ10917; SDS; SWDS; SDO1
Tractability: PROTAC: ubiquitination databases record sites on it; its protein half-life has been measured.
Gene: Protein-coding gene on chromosome 7 (66,987,680 to 66,995,693, reverse strand). Ensembl gene ENSG00000126524.
Subcellular location: Cytoplasm; Nucleus, nucleolus; Nucleus, nucleoplasm; Cytoplasm, cytoskeleton, spindle
Subcellular location (Human Protein Atlas): Cytosol; Nucleoplasm
Gene Ontology:
Molecular function: microtubule binding; protein binding; ribosome binding; RNA binding; rRNA binding
Biological process: bone marrow development; bone mineralization; cytosolic ribosome assembly; hematopoietic progenitor cell differentiation; leukocyte chemotaxis; mitotic spindle organization; rRNA processing; ribosome biogenesis
Cellular component: cytoplasm; cytosol; nucleolus; nucleus; spindle pole; nucleoplasm; spindle
Genetic constraint (gnomAD): Loss-of-function variants: 19 observed, 25.82 expected, observed/expected ratio (o/e) 0.74, 90% interval 0.51 to 1.08. The upper end of that interval is the gene's LOEUF score, 1.08, which puts it in group 4 of 6, group 1 being the genes least tolerant of losing a copy. Missense variants: 239 observed, 308.3 expected, observed/expected ratio (o/e) 0.78, 90% interval 0.7 to 0.86. Synonymous variants: 95 observed, 106.93 expected, observed/expected ratio (o/e) 0.89, 90% interval 0.75 to 1.05.
Gene-disease validity (ClinGen):
ClinGen rates the evidence that SBDS causes each of these diseases.
Shwachman-Diamond syndrome (autosomal recessive): Definitive.
Homologues: Orthologues: chimpanzee SBDS (100% identical), pig SBDS (99% identical), guinea pig SBDS (98% identical), mouse Sbds (97% identical), rat Sbds (97% identical), rabbit SBDS (95% identical), tropical clawed frog sbds (86% identical), dog SBDS (86% identical), macaque SBDS (85% identical), zebrafish sbds (84% identical), Drosophila melanogaster Sbds (60% identical), Caenorhabditis elegans sbds-1 (57% identical).
Diseases named in the same sentence as SBDS in open-access papers:
SBDS is named in the same sentence as 69 diseases in open-access papers, as found by Europe PMC text mining. Sharing a sentence is not in itself a finding about the gene and the disease. The quoted sentences say what the papers report.
Shwachman-Diamond syndrome (57 papers, 2009 to 2025). "Genetic analyses have identified pathogenic variants in the Shwachman-Bodian-Diamond Syndrome (SBDS) gene in approximately 90% of diagnosed cases." (PMID 41383570, 2025). "The same molecule also demonstrated its ability to restore SBDS protein expression in both lymphoblastoid cell lines and periodontal ligament stem cells from Shwachman–Diamond syndrome patients carrying the K62X nonsense mutation in the SBDS gene." (PMID 40420818, 2025). "Since its first publication in 2003, pathogenic variants in the SBDS gene have been detected in more than 90% of people with Shwachman-Diamond syndrome (SDS)." (PMID 36512530, 2022). "The protein encoded by the Shwachman-Bodian-Diamond syndrome (SBDS) gene is involved in ribosomal RNA processing." (PMID 36512530, 2022). "The testing of the consanguineous parents revealed a heterozygous carrier status in the father and, surprisingly, homozygosity of the SBDS variant in the mother, thus confirming the diagnosis of Shwachman-Diamond syndrome (SDS) in the fetus and the mother." (PMID 34974531, 2022). "Another notable cluster among rare gastroenterological diseases is given by the Shwachman-Diamond syndrome: 90% of all patients have a mutation in the SBDS gene, which is known to be involved in ribosome maturation, but otherwise poorly annotated." (PMID 34753928, 2021). "The SBDS founder variant (NM_016038.2:c.258+2T>C) is also worth highlighting since this is the most commonly reported variant in Schwachman-Diamond syndrome (SDS) and yet we identified it in homozygosity in at least three individuals who lack SDS features." (PMID 32552793, 2020). "The loss of Dicer1 is associated with reduced expression of the ribosome maturation factor encoded by the SBDS (Shwachman-Bodian-Diamond syndrome) gene mutated in Schwachman-Diamond syndrome, a human congenital BM failure with known leukemia predisposition." (PMID 32443460, 2020). "Shwachman-Diamond syndrome (SDS) is resulted from mutations in the SBDS gene, characterized by neutrophil dysfunction and defective RANKL-mediated upregulation of Rac227." (PMID 32341385, 2020). "For example, approximately 90% of SDS cases are caused by mutations in the Shwachman-Bodian-Diamond Syndrome (SBDS) gene, leading to the loss of SBDS protein expression." (PMID 30862070, 2019). "One patient with an isochromosome of the long arm of a chromosome 7 was then diagnosed as affected by Shwachman-Diamond syndrome, as he was found to be compound heterozygote for mutations of the SBDS gene." (PMID 29344089, 2018). "Biallelic loss of function mutations in SBDS are associated with the ribosomopathy Shwachman-Diamond syndrome, which is typified by pancreatic dysfunction, bone marrow failure, skeletal abnormalities and neurological phenotypes." (PMID 26057580, 2015). "Shwachman-Diamond syndrome (SDS) is a recessive ribosomopathy caused by biallelic loss-of-function mutations in SBDS." (PMID 26057580, 2015). "Shwachman Diamond syndrome (SDS) is caused by mutations in the Shwachman-Bodian-Diamond syndrome (SBDS) gene, which functions in ribosomal subunit joining." (PMID 26398160, 2015). "Mutations in the Shwachman-Bodian-Diamond syndrome (SBDS) gene, which are associated with Shwachman-Diamond syndrome, lead to impaired myeloid development." (PMID 26119962, 2015). "The phenotypic features of the nol9sa1022/sa1022 mutants are highly reminiscent of the tissue specific clinical features of Shwachman-Diamond syndrome (SDS) that is associated with deficiency of the SBDS (Shwachman-Bodian-Diamond Syndrome) protein." (PMID 26624285, 2015). "Shwachman-Diamond Syndrome (SDS) is an autosomal recessive disorder associated with mutation in the Shwachman Bodian Diamond Syndrome gene, SBDS, involved in ribosomal biogenesis and mitotic spindle association." (PMID 22046571, 2011). "For example, biallelic loss-of-function variants in the SBDS gene cause Shwachman-Diamond syndrome." (PMID 40766138, 2025).
Shwachman-Diamond syndrome (continued). "The Shwachman–Diamond Syndrome (SDS) is an autosomal recessive disease whose majority of patients display mutations in a ribosome assembly protein named Shwachman–Bodian–Diamond Syndrome protein (SBDS)." (PMID 35887285, 2022). "Schwachman Diamond Syndrome is caused by mutations in the SBDS gene at chromosome 7q11.21." (PMID 31709206, 2019). "Mutations within SBDS are associated with the autosomal recessive disorder Shwachman-Bodian-Diamond syndrome (or Shwachman-Diamond syndrome), which is a rare congenital disorder characterized by exocrine pancreatic insufficiency, bone marrow dysfunction, skeletal abnormalities and short stature." (PMID 30598092, 2018). "Isomorphic mutation of the SBDS gene causes Shwachman-Diamond syndrome (SDS)." (PMID 27146429, 2016). "Shwachman-Diamond Syndrome (SDS) is a rare inherited disease caused by mutations in the SBDS gene." (PMID 21695142, 2011). "Shwachman-Diamond Syndrome (SDS) is a hereditary disease caused by mutations in the SBDS gene." (PMID 19759903, 2009). "For example, we identified a patient with biallelic variants in SBDS, which is associated with Shwachman-Diamond syndrome (SDS)." (PMID 40766138, 2025). "Moreover, mutations in the SBDS gene (SBDS ribosome maturation factor) have been studied in mice to understand pancreatic defects similar to those observed in Shwachman–Diamond syndrome (SDS), the second most common cause of hereditary exocrine pancreatic insufficiency in humans." (PMID 39613794, 2024). "Shwachman-Diamond syndrome (SDS) is an inherited ribosome assembly disorder caused by compound heterozygous germline mutations in the SBDS gene, typically the combination of one null and one hypomorphic allele." (PMID 37608017, 2023). "Shwachman-Diamond syndrome (SDS) is a rare congenital disorder caused by mutations in the SBDS gene and characterized by exocrine pancreatic deficiency, hematologic dysfunction, and skeletal growth failure." (PMID 37580732, 2023). "SBDS encodes for a protein involved in ribosomal maturation and its mutation has been identified in Shwachman-Diamond syndrome (SDS), characterized by BM failure with a high risk of developing AML." (PMID 31709192, 2019). "Shwachman-Diamond syndrome (SDS) is an inherited disease caused by mutations of a gene encoding for SBDS protein." (PMID 27658964, 2016). "Shwachman-Diamond syndrome (SDS) is an autosomal recessive disorder (Online Mendelian Inheritance in Man #260400) that is caused by mutations of the SBDS gene in at least 90% of cases." (PMID 24330778, 2013). "We identified a pediatric patient presenting with SDS concomitantly diagnosed with Klinefelter syndrome, characterized by a splice-site in the Shwachman-Bodian-Diamond Syndrome (SBDS) gene and a mosaic karyotype of 47,XXY/46,XY(Klinefelter syndrome)." (PMID 41383570, 2025). "Examples of diseases indirectly affecting ribosome biogenesis are Shwachman–Diamond syndrome (SBDS gene affecting ribosomal maturation) and Treacher Collins syndrome (TCOF1 gene affecting rRNA synthesis and pre-rRNA processing)." (PMID 37606454, 2023). "Shwachman–Diamond syndrome (SDS) represents one of the most common inherited bone marrow failure syndromes and is mainly caused by SBDS gene mutations." (PMID 36835434, 2023). "The most statistically significant regulator was SBDS (Shwachman-Bodian-Diamond Syndrome), a regulator of ribosomal maturation." (PMID 32625236, 2020). "Nevertheless, the P-site loop becomes ordered upon the binding of specific ligands such as t-RNAs or assembly factors such as SBDS (Shwachman-Bodian-Diamond Syndrome)." (PMID 33227977, 2020). "An exemplary disease is Shwachman-Diamond syndrome (SDS); a rare autosomal recessive bone marrow failure disorder caused by mutation in the SBDS gene with a cumulative probability of leukemic progression of >30% at the age of 30 years." (PMID 34713241, 2020).
Shwachman-Diamond syndrome (continued). "Dysfunctional SBDS can lead to the Shwachman-Bodian-Diamond syndrome, a recessive disease defined by a complex suite of clinical features including pancreatic dysfunction, short stature and leukemia." (PMID 32625236, 2020). "The Shwachman-Bodian-Diamond syndrome protein (SBDS) was first identified as a protein, which when mutated causes the Shwachman-Diamond syndrome (SDS), an inherited disorder characterized by bone marrow failure." (PMID 31853379, 2019). "Mutations in the human orthologue of Sdo1, SBDS, are responsible for most of the cases of the Shwachman-Diamond syndrome." (PMID 28230789, 2017). "Altogether, our study provides novel genotype-function relationships and molecular insight into the function of SBDS in the Shwachman-Diamond Syndrome." (PMID 21695142, 2011). "Mutations of the human SBDS gene are associated with the condition known as Shwachman-Diamond syndrome (SDS), an autosomal recessive disorder with clinical features including hematological and skeletal abnormalities and also exocrine pancreatic insufficiency [OMIM:260400]." (PMID 19454024, 2009). "Interestingly, the chip was also exploited with Shwachman–Diamond syndrome (SDS) patient cells, a genetic bone marrow failure syndrome characterized by biallelic mutations in the SBDS gene." (PMID 41459505, 2025). "The release factors SBDS and EFL1—both mutated in the leukemia predisposition disorder Shwachman-Diamond syndrome — license entry of nascent 60S ribosomal subunits into active translation by evicting the anti-association factor eIF6 from the 60S intersubunit face." (PMID 35322020, 2022). "Shwachman–Diamond syndrome (SDS), an autosomal recessive disorder characterized by bone marrow failure, exocrine pancreatic insufficiency, and skeletal abnormalities, is caused by mutations in the Shwachman–Bodian–Diamond syndrome (SBDS) gene, which plays a role in ribosome biogenesis." (PMID 32908229, 2020). "Deficiencies in the human Sdo1 protein, the Shwachman-Bodian-Diamond syndrome protein (SBDS), are associated with Shwachman-Diamond syndrome (SDS), a congenital disorder characterized by bone marrow failure and exocrine pancreatic insufficiency." (PMID 28715419, 2017). "Finally, conversion events between the SBDS gene and its paralogous duplicated pseudogene SBDSP cause Shwachman-Bodian-Diamond syndrome, an autosomal recessive disorder with pancreatic exocrine insufficiency, hematologic dysfunction, and skeletal abnormalities." (PMID 27999401, 2016). "We searched the WangFang and China National Knowledge Infrastructure databases with the keywords “Shwachman-Diamond syndrome,” “SDS,” “SBDS gene” and “inherited bone marrow failure” for relevant articles published from January 2002 to October 2022." (PMID 37803383, 2023). "Shwachman-Diamond syndrome (SDS) is an autosomal recessive inherited disease of the SBDS gene." (PMID 32104616, 2020). "Additional clinical features were suggestive of Shwachman Diamond syndrome, although it was noted she carried only a single missense change, which was not previously reported and possibly deleterious, in the SBDS gene." (PMID 24898207, 2014). "Similarly, cryptorchidism, not reported in patients with SBDS mutations (PubMed and Google Scholar search, June 2022, using cryptorchidism AND Shwachman-Diamond Syndrome), is present in UPN 43, its prevalence in the normal population is 1.7%, and observed in about 20–35% of WDSTS cases." (PMID 35893049, 2022).
bone marrow failure (11 papers, 2012 to 2025). "A previous study by Austin and colleagues has shown that cells of SDS patients that carry a mutation of SBDS divide improperly, generating multipolar spindles during mitosis, which could contribute to bone marrow failure and leukemogenesis." (PMID 40856631, 2025). "Shwachman–Diamond syndrome (SDS) is a rare autosomal recessive disorder characterized by bone marrow failure, exocrine pancreatic insufficiency, and skeletal abnormalities, caused by loss-of-function mutations in the SBDS gene, a factor involved in ribosome biogenesis." (PMID 34948128, 2021). "An inherited bone marrow failure panel was sent from peripheral blood and revealed a novel SAMD9 variant (heterozygous c.4460A > G; p.Lys1487Arg) and two heterozygous variants of uncertain significance, TET2 and SBDS." (PMID 37160314, 2023). "Of note is SBDS’ role in stabilizing the mitotic spindle, the absence of which may lead to chromosomal instability and therefore bone marrow failure." (PMID 22709827, 2012).
neutropenia (7 papers, 2009 to 2025). A decrease in the number of neutrophils found in the blood. "SDS is another congenital form of neutropenia caused by mutations in the SBDS gene, which regulates ribosomal function and cell stress responses." (PMID 40418265, 2025). "Following molecular analysis using the ORCP he was found to have a homozygous known pathogenic mutation in the SBDS gene (c.258 + 2T) and mild neutropenia developed at around that time." (PMID 27432187, 2016). "Mutations in ELANE, HAX1, GFI1, and SBDS can confirm the diagnosis of SCN, cyclic neutropenia, or SDS." (PMID 40418265, 2025). "Congenital neutropenia is often linked to mutations in genes such as ELANE, HAX1, and SBDS." (PMID 40418265, 2025). "Congenital neutropenias due to mutations in ELANE, SBDS or HAX1 or in the setting of glycogen storage disease (GSD) which is caused by SLC37A4 mutation, often require prolonged granulocyte colony stimulating factor (G-CSF) therapy to prevent recurrent infections and hospital admission." (PMID 31788408, 2019). "Altogether, our data indicate a role for SBDS in the cell division in human myeloid progenitor cells, which may provide an explanation for the observed neutropenia and leukemia in SDS." (PMID 19759903, 2009). "SBDS co-localizes with the mitotic spindle, suggesting a role for SBDS in the cell division process, which corresponds to the decreased proliferation capacity of SDS-patient bone marrow CD34+ hematopoietic progenitor cells in our culture system and also to the neutropenia in SDS patients." (PMID 19759903, 2009).
bone marrow failure syndrome (3 papers, 2022 to 2025). "On the other hand, SBDS pathogenic variants have been associated to the autosomal recessive syndrome Shwachman-Diamond 1, that is an inherited bone marrow failure syndrome characterized by enhanced cancer predisposition." (PMID 36428697, 2022).
breast carcinoma (3 papers, 2019 to 2020). "Mutation of the SBDS gene is known to increase the risk of leukemia, but its association with solid tumors, including breast cancer, remains unknown." (PMID 31853379, 2019). "In a previous study PAX5, TMPRSS2, and SBDS genes that we are investigating were reported to be methylated more than 60% in breast cancer and malignant melanoma cell lines." (PMID 30792990, 2019). "In this regard, SBDS could be a potential prognostic marker and therapeutic target in breast cancer patients." (PMID 31853379, 2019). "In addition, SBDS was negatively correlated to the survival of breast cancer patients, implying that SBDS is a key regulator of stiffness-dependent apoptosis in breast cancer cells." (PMID 31853379, 2019). "Furthermore, SBDS was identified as a promising regulator through screening on both stiffness-dependent mRNA expression of apoptosis regulators and hazard ratio of breast cancer patients." (PMID 31853379, 2019). "However, the methylation status of selected PAX5, TMPRSS2, and SBDS genes was examined in cell lines but not primary tumor tissue of patients with breast cancer and malignant melanoma in the literature." (PMID 30792990, 2019).
endometrial cancer (3 papers, 2020). Primary or metastatic malignant neoplasm involving the endometrium (mucous membrane that lines the endometrial cavity). "Immunohistochemical analysis based on The Human Protein Atlas database enumerated a significant upregulation of PSMC4, NR3C1, SBDS, and CBLC in endometrial cancer tissues, relative to normal tissues." (PMID 33292199, 2020).
leukemia (3 papers, 2009 to 2025). A malignant (clonal) hematologic disorder, involving hematopoietic stem cells and characterized by the presence of primitive or atypical myeloid or lymphoid cells in the bone marrow and the blood. "Most interestingly, Nucleophosmin (NPM1), a frequently mutated gene in leukemia, which encodes for a multifunctional nucleolar protein implicated in both ribosome biogenesis and centrosome duplication, was recently shown to interact with SBDS." (PMID 19759903, 2009).